CD4 (CD4 molecule)
Diseases named in the same sentence as CD4 in open-access papers (continued):
Sharing a sentence is not in itself a finding about the gene and the disease.
AIDS (continued). "The results of the Cox proportional hazards model analysis demonstrated a significant association between sex, age, transmission route, baseline CD4+ T lymphocyte count and WHO clinical stage and AIDS-related mortality among individuals living with HIV/AIDS." (PMID 38454987, 2024). "The CD4 T lymphocyte count is a predictor for the progression of disease (AIDS), survival and response to ART in PLHIV." (PMID 38478483, 2024). "A CD4(+) T cell count below 200 cells/μL indicates a diagnosis of AIDS after HIV infection, signifying severe impairment of the immune system." (PMID 38760740, 2024). "Unexpectedly, GB virus C (GBV-C), a human non-pathogenic lymphotropic flavivirus, co-infects HIV-1 target cells, resulting in lower HIV RNA levels, slower progression to AIDS, improved survival, and higher CD4+ T cell counts in co-infected patients." (PMID 38787201, 2024). "Talaromyces marneffei mainly affects immunocompromised individuals, particularly those with AIDS, especially when the CD4+ T cell counts are below 50 cells/μL." (PMID 39452161, 2024). "Patients living with HIV/AIDS who have weakened systems, as indicated by low CD4 cell counts, experience a significant decrease in both their humoral and cellular immunity." (PMID 38803735, 2024). "They conclude that HBsAg levels tend to be approximately 1 log higher among PLWH with low CD4 counts or in those with advanced AIDS." (PMID 39135958, 2024). "After U.S. Food and Drug Administration (FDA) approval of azidothymidine (AZT), the first drug for treating AIDS, decisions regarding when to begin anti-retroviral therapy were based on CD4 T-cell counts." (PMID 39408593, 2024). "In this report, we described the evolution of the T CD4+/CD8+ cell ratio in long-term cART users from Sao Paulo, Brazil, and the association of the CD4+/CD8+ ratio with AIDS incidence." (PMID 38324873, 2024). "Changes of CD4+/8+ in HIV/AIDS patients (Full dataset, CD4+ baseline > 200, baseline CD4+≤ 200) according to treatment during follow-up after PSM." (PMID 39240822, 2024). "The median CD4 count of AIDS patients was 11 cells/μL (range: 1-198), and 33% had concurrent opportunistic infections." (PMID 38943055, 2024). "Among the LPAD, 2,842 had at least one CD4 count record within three months of initial HIV/AIDS diagnosis." (PMID 38896338, 2024). "The goal of this study was to identify the key factors that change over time in CD4 cells for HIV/AIDS patients receiving ART follow-up in northern Ethiopia." (PMID 39367327, 2024). "Research suggests that the gut microbiota plays a significant role in the decline of CD4 T cell counts, contributing to AIDS pathogenesis." (PMID 39597610, 2024). "The conclusion from the data is obvious: the spleen is the “graveyard” of CD4+ cells in patients with relapsing VL and AIDS." (PMID 38491526, 2024). "A diagnosis of AIDS is based on a CD4+ T lymphocyte count of <200 and/or the presence of an AIDS-defining illness." (PMID 39398847, 2024). "Upon routine hospital screening, the patient was found to be positive for HIV with a CD4 count of 20, indicative of AIDS, prompting an infectious disease consultation." (PMID 39439637, 2024). "When stratifying studies according to CD4+ count (<200 cells/μL (AIDS) or >200 cells/μL (non‐AIDS)), only one study had a mean cohort CD4+ count >200 cells/μL69 and this study reported that the inflammatory profile was associated with NCI/HIVE." (PMID 38282400, 2024). "In another report, older age was associated with lower CD4 + counts, advanced stages of HIV disease, bedridden functional status, and delayed diagnosis of HIV/AIDS." (PMID 38549051, 2024). "Before the initiation of ART, 60.1 % (n = 110) of the patients had >50 copies/mL and 32.2 % (n = 59) had AIDS-defining conditions (<200 CD4 cells/mm3)." (PMID 39398487, 2024).
AIDS (continued). "Because their CD4 cell counts were lower at baseline and they had a functional status of bedridden, the majority of HIV/AIDS patients on ART had substantial predictors on the change of CD4 cell count over time." (PMID 39367327, 2024). "Populations were defined according to ECDC guidelines for aggregated data: annual total number of HIV and/or AIDS diagnosis, deaths and stratification according to CD4 cell count at diagnosis (≥500, 350–499, 200–349 and <200 cells/mmc)." (PMID 39513741, 2024). "In advanced HIV, especially in those with inflammatory complications, the depletion of CD4+ T cells during AIDS and chronic stimulation from persistent viremia leads to a dysregulated and exhausted T cell compartment." (PMID 38564303, 2024). "Five (27.8%) had a previous AIDS diagnosis, and median CD4 T cell nadir was 59 (IQR: 12.5–331.3) cells/μL." (PMID 38188525, 2024). "Two of the untreated controls were rapid progressors showing a drastic decline in CD4 + T cells to 44 and 275 cells/μL and progression to simian AIDS within 6 months." (PMID 39632836, 2024). "CD4 counts at the time of the AIDS event were highest among PLHIV who experienced the outcome after > 6 years of continuous ART (median 397 cells/μL, IQR 139–738)." (PMID 38381307, 2024). "It is crucial to strengthen the follow-up and screening of HIV/AIDS patients, especially among the middle-aged population with CD4+ T lymphocyte counts below 100/μL, to ensure they receive ART as early as possible." (PMID 39205307, 2024). "The average HIV follow‐up was 16.3 years, with a CD4 nadir of 70/mm3 and initial viral load of 96,000 copies/ml; 15% had an AIDS‐defining event." (PMID 39513741, 2024). "Patients who drink alcohol (range: 21.6%-23.5%) or use (PWUD range: 16.7%-20.1%) or inject (PWID range: 15.5%-20.1%) drugs were most likely to have ART deferred, even at AIDS-defining CD4 counts." (PMID 39028735, 2024). "In our time period analyses, we again observed a similar distribution in the first period between 1999 and 2009, in which a previous AIDS event and CD4 count were selected in the majority of the bootstrapped samples, however not PWID." (PMID 38381307, 2024). "The repression of MHC class II molecules in professional antigen-presenting cells (APCs) was also observed during HIV infection in humans and serves as one of the immunodeficiency mechanisms of CD4+ T cells in AIDS." (PMID 39283947, 2024). "Historically associated with HIV/AIDS, PJP has traditionally been diagnosed in HIV-positive individuals with CD4+ T lymphocyte counts < 200 cells/mm3." (PMID 38919241, 2024). "A CD4 count of ≤ 200 cells/mm3 indicates the patient has AIDS and is likely to develop life-threatening infections or cancers." (PMID 39430110, 2024). "In PWHs and NHPs that progress to AIDS, effector memory CD4+ T-cells are preferentially depleted, with a massive depletion of activated memory CD4+ T-cells in the lamina propria of the gut and, to a lesser extent, in the peripheral blood and lymph nodes (LNs)." (PMID 38932264, 2024). "Nevertheless and compared across the HIV-ICs analysed, participants diagnosed with AIDS-defining conditions tend to have the lowest CD4 counts with almost three quarter of participants with less than 350 cells/μl." (PMID 39476279, 2024). "A low CD4 count, a previous AIDS-defining condition at ART initiation and transmission through intravenous drug use were identified as overall meaningful prognostic factors of the outcome." (PMID 38381307, 2024). "Clinical studies provided evidence that HIV-1 patients co-infected with GBV-C showed lower HIV-1 RNA levels, slower progression to AIDS, improved survival, and higher CD4+ T cell counts compared to patients infected with HIV-1 only." (PMID 38787201, 2024). "When human immunodeficiency virus type 1 (HIV-1) was identified as the causative agent of AIDS, and the first clinical trials for HIV anti-viral therapies were conducted, CD4 T-cell counts were part of the enrollment criteria for the trials." (PMID 39408593, 2024).
AIDS (continued). "Another study from France defining interruptions using gaps of >12 months found that almost half of returning PWH had CD4+ cell count <200 or AIDS, and that those experiencing these interruptions were five times more likely to die." (PMID 38742863, 2024). "P1 was an ART-naive individual diagnosed with AIDS (CD4 T cell count 47 cells/μL) and concurrent neurosyphilis at his initial study visit." (PMID 38587074, 2024). "Investigations focusing on the CRF01_AE subtype highlight a significantly rapid disease progression from HIV-1 infection to clinical AIDS stage and a drop in CD4+ T cell count below 200/μL, with median times of 7.2 years and 6.5 years, respectively." (PMID 38994006, 2024). "Patients with AIDS who underwent splenectomy had an increase in CD4+ number, and paradoxically, the CD4+ population was higher in the spleen of patients with HIV." (PMID 38491526, 2024). "People living with HIV/AIDS whose CD4 counts <200 cells/mm3 was 3.77 times (AOR = 3.77; 95% CI: 1.01–13.15; p-value = 0.04) more likely to get an infection with intestinal parasites than those with CD4 counts >500 cells/mm3." (PMID 39664543, 2024). "Due to this, the goal of the current study was to pinpoint the main indicators of CD4 cell changes over time in HIV/AIDS patients who were being monitored." (PMID 39367327, 2024). "Our lab previously demonstrated that a rapid CD4 + T-cell decline predicted progression to AIDS less reliably than increasing monocyte turnover (MTO)." (PMID 39822268, 2024). "For the particular change in CD4 cells of HIV/AIDS patients, the multivariable analysis of random intercept and slope (RI-RS) model is sufficient." (PMID 39367327, 2024). "HIV is a single-stranded RNA Retrovirus, which mainly targets CD4+ T cells, inducing progressive and severe immune dysfunction leading to AIDS." (PMID 39273118, 2024). "Identifying these predictors that affect change of CD4 cells on HIV/AIDS patients also helps health professionals to facilitate proper management and monitoring of the health care intervention on ART program." (PMID 39367327, 2024). "Acquired immunodeficiency syndrome (AIDS) is the most advanced stage of the disease that is associated with higher HIV viral load and low CD4+ T cell count." (PMID 38494500, 2024). "AIDS, defined by a CD4+ count below 200 cells/mm3 or the presence of an AIDS-defining illness, leads to severe immunosuppression and life-threatening complications." (PMID 39599491, 2024). "KICS is prone to occur in AIDS patients with a lower CD4+ cell counts, often accompanied by HHV-8 infections." (PMID 39759142, 2024). "HIV late presenters were defined as individuals presenting with a CD4 count below 350 cells/μL or with an AIDS-defining event, according to the European Late Presenter Consensus working group." (PMID 39037975, 2024). "Years after the chronic infective stage, the patient progresses to AIDS which is Stage 3, where the CD4 count in the body is significantly reduced to levels <200 cells/cubic mm, making the patient prone to many opportunistic infections." (PMID 39050280, 2024). "In our study, HIV/AIDS patients who had baseline CD4 count ≤200 cell/μL increased by 41% more than among HIV/AIDS patients who have baseline CD4 count > 200 cell/μL (AHR = 1.41 [1.18, 1.69])." (PMID 38410498, 2024). "PLHA, particularly those with low CD4 counts and reduced immune surveillance, should be regularly screened for aggressive AIDS-defining malignancies to facilitate early diagnosis and efficient management." (PMID 39651017, 2024). "Conducted at a university hospital in Brazil from March 2015 to July 2017, it included AIDS patients over 18 years old with a CD4+ count ≤ 200 cells/mm3." (PMID 39057375, 2024). "Mean age at baseline 47.0 years; mean time on ART 11.3 years; history of AIDS 29.2%; mean CD4 515/μl." (PMID 39513741, 2024). "When PWH have low CD4 cell counts, AIDS, opportunistic infections, or death are more likely to occur." (PMID 38778273, 2024).
AIDS (continued). "Patients at advanced clinical stages of HIV/AIDS often had significant immunosuppression, characterized by lower CD4 counts." (PMID 39361573, 2024). "The CD4+ count and CD4/CD8 ratio is correlated with the status of immune function of AIDS patients, besides early and maintenance therapy in AIDS patients are important to increase the CD4+ count and CD4+/CD8+ ratio and the immunological reconstitution." (PMID 39742334, 2024). "Both viruses co-circulate in Western Africa, and HIV-2 causes a milder disease compared to HIV-1, characterized by a lower plasma viral load and infectivity and a slower decline of CD4+ T cells and progression to AIDS." (PMID 38787201, 2024). "Early clinical usage of CD4 immunophenotyping established a correlation between CD4 count and AIDS stage." (PMID 38398466, 2024). "A key indicator of AIDS is a CD4 count below 200 cells/μL, with advanced AIDS characterized by a severely weakened immune system that predisposes patients to opportunistic infections." (PMID 39575001, 2024). "We also assessed trends in new HIV diagnoses and late presentation (CD4 count of <350 cells/μl and/or AIDS at diagnosis), and disengagement from care." (PMID 39118295, 2024). "While initial CMV infection often presents as a mild, self-limiting illness with symptoms like fever, fatigue, and lymphadenopathy, it becomes significant in AIDS, particularly with CD4+ counts below 50 cells/mm3." (PMID 39100809, 2024). "Even with successful ART, PLWH often have chronic immune activation and elevated inflammation that has been linked with poor CD4 + T cell recovery and the premature onset of HIV-related non-AIDS-defining comorbidities." (PMID 38310301, 2024). "Human immunodeficiency virus (HIV)-1 is an etiological agent of Acquired Immunodeficiency Syndrome (AIDS), a devastating infectious disease that targets the immune system, primarily infecting the CD4+ T cells and myeloid cells." (PMID 38891030, 2024). "This study suggests that the presence of AIDS and COVID-19 are factors associated with the risk of D-VL, while the duration of HAART and prescriber’s perception of adherence to therapy and Nadir CD4+ T-cell levels are associated with a lower risk of D-VL." (PMID 38787211, 2024). "Owing to an insufficient frequency of occurrences in each category, this study was not originally designed to explore the association between the CD4/CD8 ratio and specific non–AIDS-defining events, notably liver damage." (PMID 37846087, 2024). "In severely immunosuppressed patients, such as those with HIV/AIDS and a CD4 T-cell count below 100 cells/mm3, meningitis symptoms can manifest more acutely." (PMID 39452161, 2024). "Regarding the CDC and National HIV/AIDS Strategy guidelines that define retention according to CD4 or viral load tests, we recommend extending the window of testing to ≥2 CD4 or viral load tests at least 6 months apart in 12–24 months." (PMID 38312216, 2024). "A diagnosis of AIDS is made when the CD4+ T-cell count falls below 200 cells/mm3 or when certain opportunistic infections or cancers arise." (PMID 39867026, 2024). "The AIDS patients with neurological diseases other than PML were positive in 25% of cases despite a similar degree of immune deficiency, based on their CD4 T cell counts, to that of patients with active PML." (PMID 39086476, 2024). "Limitations of our study include the substantial proportion of missing CD4 and VL values at the time of the AIDS event." (PMID 38381307, 2024). "In individuals with immunosuppression due to HIV, NHL is frequently observed in those with low CD4 count (usually less than 100 cells/mm3), high viral load, advanced age, and prior AIDS-related conditions." (PMID 38803735, 2024). "Summary statistics of the longitudinal CD4 cell count of HIV/AIDS adult patients across visiting time groups." (PMID 38913649, 2024).
AIDS (continued). "Reflecting the recruitment strategy, nearly half (118/250; 47.2%) had experienced advanced HIV infection, either a previous AIDS-defining diagnosis (74/250, 29.6%) or a nadir CD4 count < 200 cells/mm3 (44/250, 17.6%)." (PMID 38594459, 2024). "Another test to guide the differential diagnosis of space-occupying lesions in AIDS patients is the CD4 cell count." (PMID 39473656, 2024). "Immunosuppressing conditions were present in 48.0% of patients, including HIV infection/AIDS, reported in nearly one-third of patients (78.6% had CD4 cell counts <200/μL)." (PMID 38674763, 2024). "Indicators of impaired immune functioning at treatment initiation, i.e., a low CD4 count, a previous AIDS-defining condition and transmission through intravenous drug use, showed to be the most meaningful prognostic factors." (PMID 38381307, 2024). "The large spleens of VL and AIDS patients highlight the importance of this co-localization with respect to the sharp decrease in CD4+." (PMID 38491526, 2024). "The longitudinal measurement of the mean change of the square root of the CD4 cell count and its association with the survival time of HIV/AIDS patients was explored using a joint model." (PMID 38913649, 2024). "The fungus Cryptococcus neoformans is responsible for >100,000 deaths annually, mostly in persons with impaired CD4+ T-cell function such as AIDS." (PMID 38980038, 2024). "Antiretroviral Treatment (ART) since 1996 has substantially improved outcomes for PLWH, including suppressing viral loads to an undetectable level, restoring CD4+ T-cell counts, and decreasing AIDS-related morbidity and mortality." (PMID 38167855, 2024). "According to the World Health Organization on HIV/AIDS, a CD4+ lymphocyte count below 200 cells per liter is generally considered a marker of AIDS stage (clinical stage III)." (PMID 39076997, 2024). "In this regard, HIV/AIDS patients with cryptococcal meningoencephalitis typically exhibit minimal inflammation due to their reduced number of CD4+ T cells." (PMID 39334365, 2024). "HAART has significantly improved the immune function of individuals living with HIV/AIDS by suppressing the replication of the virus and increasing cluster of differentiation 4 (CD4) T-cell counts." (PMID 39599491, 2024). "In order to properly treat HIV/AIDS, infection should be detected as soon as feasible; when the person’s CD4 cell count exceeds 350 cells/mm3." (PMID 38926656, 2024). "Irrespective of which key populations studied, physicians would defer ART more often for those with a CD4 count consistent with AIDS-defining diagnosis (<200 cells/mL) relative to those with higher CD4 counts." (PMID 39028735, 2024). "Among the 75 unsuppressed HIV RNA (usRNA), including six naive; median age was 53.1 years, 30.7% were women, 16% were at AIDS stage, median BMI was 24.8 and median CD4 count was 525/mm3 [IQR 277–947], median HIV viral load was 205 cp/ml [IQR 84–5774]." (PMID 39513741, 2024). "CD4+ lymphocyte infection and destruction result in the severe immunosuppression features of AIDS, allowing the establishment of secondary infections." (PMID 37110574, 2023). "Remarkably, CBA/J and A/Jcr CD4-depleted mice, mimicking AIDS patients, were largely protected against cryptococcosis when vaccinated with the live sre1ΔZNF2oe cells." (PMID 37338404, 2023). "A study performed between 2009 and 2012 found 58% of newly diagnosed in Sweden to be late presenters (CD4 <350 cells/μL or AIDS) and 38% to have an advanced infection (<200 cells/μL or AIDS)." (PMID 36931676, 2023). "Identifying a substantial part of RRMM patients with CD4+-T-cell-numbers comparable to patients with AIDS stage III suggests an increased need for prophylaxis of opportunistic infections in this patient group." (PMID 37152008, 2023). "AIDS-defining illness/ advanced HIV disease: CD4+ T-cell counts drop below 200 per μl and there is increased susceptibility to opportunistic infections or neoplasms." (PMID 37214076, 2023).